EGFR (epidermal growth factor receptor)
Diseases named in the same sentence as EGFR in open-access papers (continued):
Sharing a sentence is not in itself a finding about the gene and the disease.
pancreatic cancer (1,009 papers, 2002 to 2026). "Our Western Blot experiments confirmed large diversity in the expression proteins associated with the EGFR signaling pathway in tested pancreatic cancer cells." (PMID 39916650, 2025). "This construct combines the well-characterized RGD peptide with GE11, a non-mitogenic peptide ligand for EGFR, allowing for simultaneous targeting of integrins and EGFR, both of which are implicated in pancreatic cancer progression and resistance to therapy." (PMID 40869454, 2025). "Another critical pathway implicated in pancreatic tumor progression is the EGFR signaling pathway, which regulates various aspects of tumor cell behavior and contributes to resistance to chemotherapy and chemoradiation." (PMID 40282495, 2025). "Ras mutations are frequent in lung and pancreatic cancers, but in several mouse models of these cancers, oncogenic Ras activity requires EGFR activation and tumor growth is reduced by EGFR ablation." (PMID 41132131, 2025). "The dual targeting of KRAS mutations and EGFR demonstrated greater therapeutic effectiveness in pancreatic cancer management compared to single-agent approaches." (PMID 39770538, 2024). "Based on KEGG analysis, significant DEGs following IM exposure at 5 dpi were associated with the “EGFR tyrosine kinase inhibitor resistance” and “pancreatic cancer” pathways, while AE exposure was again associated with “T cell receptor signaling”." (PMID 39772117, 2024). "Previous studies have demonstrated that EGFR is mostly upregulated in pancreatic tumors and is associated with a worse prognosis." (PMID 38459558, 2024). "The human epidermal growth factor receptor type 1 (HER1/EGFR) is overexpressed in pancreatic cancer and associated with poor prognosis and tumor progression." (PMID 38459558, 2024). "This is consistent with findings in colorectal and pancreatic cancers, where EGFR overexpression has been linked to a poor prognosis and an increased risk of metastasis." (PMID 39123483, 2024). "In mice, GE11-linked micelles can deliver GEM to EGFR-expressing pancreatic cancer cells, act on tumor blood vessels and show significant inhibition of pancreatic tumor growth." (PMID 38474185, 2024). "Erlotinib, is one of the most popular EGFR inhibitors which is currently marketed to treat many types of cancer with EGFR gene mutations (including non-small lung and pancreatic cancer)." (PMID 37716963, 2023). "Scientific evidence has suggested that the overexpression of EGFR is associated with a poor prognosis of pancreatic cancer." (PMID 37686675, 2023). "Data from NSCLC patients demonstrated that KRAS mutation is very low in NSCLC but high in pancreatic cancer, and that it has a significantly lower benefit from EGFR tyrosine kinase inhibitor." (PMID 36975494, 2023). "In a previous study, we correlated the loss of EGFR in a pancreatic cancer mouse model to a significantly reduced amount of RASGTP molecules." (PMID 37341059, 2023). "Our study has provided a direct association between pancreatic cancer survival and the overexpression of EGFR, beta-catenin, cyclin D1, CDK4, and ErbB2." (PMID 35448172, 2022). "Among the 77 target genes, over expression of EGFR has been previously identified in pancreatic tumors and it is associated with poor prognosis and disease progression." (PMID 36531045, 2022). "Anti-EGFR antibody panitumumab was linked to a fluorescent fluorophore (IRDye800CW), and a clinical trial was performed in patients with pancreatic cancer undergoing surgery (NCT03384238)." (PMID 35892707, 2022). "The development of metastases in pancreatic cancer was associated with ciRS-7 regulating miR-7-mediated EGFR/STAT3 signaling." (PMID 35313983, 2022). "Although its mutations are notably lower than EGFR, previous research has identified this component as a potential target to consider in some patients with pancreatic cancer." (PMID 35448172, 2022).
pancreatic cancer (continued). "The overexpression of the epidermal growth factor receptor (EGFR) is reported in the majority of pancreatic carcinomas (70–90%) and is associated with a worse prognosis." (PMID 36291891, 2022). "Up-regulation of EGFR has been linked to poor disease prognosis, invasion, and aggressive clinical behavior of pancreatic cancers." (PMID 34552882, 2021). "Integrin-αvβ3-mediated stemness had been linked to the resistance of breast, lung, and pancreatic cancer to the EGFR inhibitor erlotinib in recent studies." (PMID 34831064, 2021). "AREG, a ligand of epidermal growth factor receptor (EGFR), is abnormally expressed in multiple types of cancers, such as pancreatic cancer, implicated in mediating the motility, metastasis, and proliferation of tumor cells." (PMID 35237609, 2021). "Transcriptional profiling of macrophages from synovial fluids of patients suffering from rheumatoid arthritis (RA) and pancreatic cancer, has further implicated potential roles of the EGFR signaling pathway in pain." (PMID 34054523, 2021). "This seems to be important, as the EGFR pathway plays an important role in Ras‐mutated pancreatic cancers, with direct impacts on the ERK and AKT signalling pathways." (PMID 31957261, 2020). "Erlotinib has also shown encouraging results in the treatment of pancreatic cancer with EGFR mutations." (PMID 32784650, 2020). "Previously, EGFR has been linked to pancreatic tumor size, advanced clinical staging, and poor survival." (PMID 33213062, 2020). "ARF6 is also associated with potentiation of additional growth factor receptors, including epidermal growth factor receptor (EGFR) signaling, and has been associated with beta 1 integrin signaling and pancreatic cancer metastasis to the liver." (PMID 31320995, 2019). "Collectively, these findings suggested that EGFR is closely associated with tumor initiation, development, and metastasis in pancreatic cancer." (PMID 30449278, 2018). "Erlotinib (Tarceva®) is another EGFR small molecule inhibitor approved by the FDA for the treatment of NSCLC with specific EGFR mutations and pancreatic cancer." (PMID 28841181, 2017). "EGFR overexpression has been observed in 30%–89% of pancreatic cancers and is associated with advanced disease, poor survival and metastasis." (PMID 29262554, 2017). "It was found by RT-PCR that the expression of EGFR was associated with the expression of B7-H3 in the pancreatic cancer cell resistant to gemcitabine, and the upregulation of B7-H3 slacked gemcitabine-induced apoptosis in Panc-1 cells." (PMID 29088829, 2017). "Although the Kirsten rat sarcoma viral oncogene homolog (KRAS) is mutated and activated in > 90% of pancreatic cancers, EGFR expression has also been shown to be essential for KRAS‐driven pancreatic ductal adenocarcinoma." (PMID 28755527, 2017). "Overexpression of EGFR type 1 (ErbB1/HER1) occurs in >90% of pancreatic cancer and is associated with a poorer prognosis." (PMID 28445400, 2017). "The current study investigated the association between EGFR expression and pancreatic cancer outcome in an East Asian population." (PMID 27399694, 2016). "Further, chronic pancreatitis that develops in Spink3−/−;XXSPINK1 mice is associated with increases in proliferation and pancreatic levels of proteins implicated in the development of pancreatic cancer, such as EGFR, HER2, and RAS." (PMID 27845447, 2016). "Recently, Korc and coworkers reported that downregulating Tat-interacting protein 30 (TIP30) and upregulating EGFR by miR-10b microRNA caused EGF-mediated invasion in pancreatic cancer." (PMID 27240340, 2016). "Our study was conducted in Taiwan, where the majority of the population is of Chinese descent, and the pancreatic cancer EGFR mutation rate was 56%." (PMID 26046796, 2015).
pancreatic cancer (continued). "Currently, pancreatic cancer is the 7th leading cause of cancer death among the Chinese, making EGFR mutation detection an important issue in the treatment of pancreatic cancer." (PMID 26046796, 2015). "The EGFR mutation profile in the Chinese population analyzed in this study can be used to predict treatment response and survival in pancreatic cancer patients receiving gemcitabine plus erlotinib." (PMID 26046796, 2015). "Erlotinib-mediated disease control in EGFR-mutated pancreatic cancer patients is modest, with many patients achieving stable disease (85%)." (PMID 26046796, 2015). "In the present study, we used direct sequencing to detect EGFR mutations and confirmed by next-generation sequencing, which accurately predicted treatment response and survival in Chinese pancreatic cancer patients." (PMID 26046796, 2015). "One potential mechanism implicated in prostate and pancreatic cancers involves direct stimulation of cell signaling pathways through interaction with the epidermal growth factor receptor (EGFR)." (PMID 26437224, 2015). "Owing to these differences in the mutation profiles of EGFR for pancreatic cancer, compared with other cancers, commercially available EGFR mutation detection kits cannot replace direct sequencing." (PMID 26046796, 2015). "Improvement in OS for pancreatic cancer patients treated with erlotinib was apparent in our study because of the high proportion of cases with EGFR mutations compared to other studies." (PMID 26046796, 2015). "Gemcitabine plus erlotinib is more effective than gemcitabine alone for treating metastatic pancreatic cancer patients, especially those with EGFR mutations." (PMID 26046796, 2015). "EGF was used to stimulate cell migration because EGFR is overexpressed in pancreatic cancer and is linked with development, invasion, and decreased survival in pancreatic cancer." (PMID 25568667, 2014). "We have found that exposure of the pancreatic cancer cells to 3-Cl-AHPC resulted in 4-fold increase in miR-134 levels with an associated marked inhibition of EGFR mRNA and protein levels." (PMID 23675407, 2013). "Treatment of pancreatic cancer cells with isoflavone compounds (including 70.54% genistein), increased miR-146a expression, causing downregulation of EGFR, MTA-2, IRAK-1, and NF-κB, resulted in inhibition of cell invasion." (PMID 22928040, 2012). "The human HER1/EGFR is overexpressed in many pancreatic tumors and is associated with more aggressive disease and poorer outcome." (PMID 21922022, 2011). "On the other hand, EGFR was found to be expressed in 69% of cases of pancreatic cancer, and high expression was weakly associated with longer survival." (PMID 24212612, 2011). "Our study aimed to investigate potential further causes for the failure of EGFR-directed therapy in pancreatic cancer." (PMID 24212612, 2011). "The PI3K/Akt/mTOR pathway is activated in pancreatic cancer by overexpression or activation of EGFR and insulin-like growth factor (IgF1R), by PTEN loss or secondary to k-ras mutation and activation of the Ras/Raf/MEK pathway." (PMID 20630061, 2010). "The EGFR inhibitors cause a decreased proliferation in the pancreatic cancer cell lines." (PMID 36556296, 2022). "Although it is contradictory that mTOR plays negative roles in autophagy, it shows the collaborate of mTOR and autophagy mediated by STYK1 at least in the cases of EGFR-TKIs resistance or pancreatic cancer with activating KRAS mutations and high basal autophagy." (PMID 37192859, 2022). "In this study, we fabricated an anti-EGFR and anti-fibroblast activation protein bispecific antibody-targeted liposomal irinotecan (BS−LipoIRI), which could specifically bind to pancreatic cancer cells and tumor-associated fibroblasts." (PMID 35745775, 2022).
pancreatic cancer (continued). "Furthermore, EGFR feedback activation after STAT3 inhibition is the cause of resistance to therapy in pancreatic cancer." (PMID 35681787, 2022). "AMD may be transformed into pancreatic intraepithelial lesions (PanINs) in the progress of activating Kras mutations or persistent epidermal growth factor receptor (EGF-R) signaling, eventually leading to the occurrence of pancreatic cancer." (PMID 34249722, 2021). "EGFR overexpression is common in pancreatic cancer patients and is associated with poor prognosis." (PMID 33546207, 2021). "Also, progression of pancreatic cancer is linked with up-regulation of EGFR and the glycoprotein over-expression has been noticed in human pancreatic cancer, a cell line that is up to 85% of ductal adenocarcinomas whereas percentage of silent mutation was 81%." (PMID 34535145, 2021). "GP1.4 is an anti-MUC1 antibody that caused internalization of EGFR in pancreatic cancer cells." (PMID 33167508, 2020). "In addition, mutated K-Ras and overexpressed EGFR is present in > 90% and 30–50% of pancreatic cancers, respectively, resulting in downstream MEK/ERK pathway overactivation." (PMID 31142371, 2019). "Furthermore, a key role of integrin αvβ3 as a cancer stem cell driver associated with resistance to EGFR inhibitors has been demonstrated in breast, lung, and pancreatic carcinomas." (PMID 30682838, 2019). "In addition, increased expression of murine RNase5 and EGFR activation are associated with tumor development in the KrasG12D-driven transgenic pancreatic cancer mouse model." (PMID 30449278, 2018). "This indicated that activation of B7-H3 by 4H7 induced variations in the levels of downstream molecules of ERK1/2, EGFR, and IκB, which might be associated with pancreatic cancer resistance to gemcitabine chemotherapy." (PMID 29088829, 2017). "Similarly, erlotinib, an effective inhibitor of the actively mutated epidermal growth factor receptor (EGFR), originally approved for the treatment of advanced pancreatic cancer, has now shown efficacy for non-small cell lung and various other cancers." (PMID 29050243, 2017). "Moreover, the levels of products of proto-oncogenes implicated in the development of pancreatic cancer, such as EGFR, HER2, and RAS, dramatically increased in pancreas of Spink3−/−;XXSPINK1 mice at 8 weeks." (PMID 27845447, 2016). "EGFR is the representative receptor underlying various tumor phenotypes, such as proliferation, anti-apoptotic advantage, migration, and invasion in malignant tumors including pancreatic cancers." (PMID 27175782, 2016). "In addition, we selected 24 targets of the kaempferol using the TCMSP database, and ascertained that anti-cancer effects of kaempferol treatment in pancreatic cancer cells were caused by the blockade of EGFR related Src, AKT, ERK1/2 signaling pathway." (PMID 27175782, 2016). "Our study first found that EGFR mutations are common in Chinese pancreatic cancer patients." (PMID 26046796, 2015). "Detection of EGFR mutations can be used to identify the subgroup of patients with pancreatic cancer in whom EGFR may be essential for tumor growth and who would thus benefit from treatment with erlotinib." (PMID 26046796, 2015). "However, a strong association was still detected between EGFR mutations and the efficacy of erlotinib in pancreatic cancer." (PMID 26046796, 2015). "Whether KRAS mutations are associated with less efficient EGFR-directed targeted therapy in pancreatic cancer patients remains controversial and requires further investigation." (PMID 26046796, 2015). "The presence of EGFR-activating mutations in Chinese patients emphasizes ethnic, geographic, and environmental variations in pancreatic cancer mutation profiles that could result in different responses to erlotinib treatment." (PMID 26046796, 2015). "HER-2 and EGFR are usually used as clinical markers for the diagnostic of pancreatic cancer." (PMID 25029561, 2014).
pancreatic cancer (continued). "Furthermore, KRAS and EGFR mutations coexisted in 4 patients (2 patients with pancreatic cancer, 1 with CRC and 1 with NSCLC)." (PMID 25313136, 2014). "The expression of a number of proteins has been shown to be associated with poor survival of patients with pancreatic cancer, including expression of epidermal growth factor receptor (EGFR), insulin-like growth factor-1 receptor (IGF-1R), heat shock protein-27 (HSP27) and VEGF." (PMID 23140395, 2012). "To date, several studies have explored alterations in the EGFR pathway in pancreatic cancer that are predictive factors for EGFR inhibition, such as EGFR mutations or amplifications and these reports have failed to document a meaningful prevalence of such alterations." (PMID 24212772, 2011). "Furthermore, EGFR is one of the well-known CDGs with a causal role in pancreatic cancer." (PMID 38716727, 2024). "Inhibition of AKA in pancreatic cancer cells causes increased mitotic arrest and apoptosis, leading to decreased proliferation and tumorigenicity, with similar apoptotic synergy observed when added to EGFR inhibition in resistant pre-clinical models of EGFR-driven NSCLC." (PMID 35907014, 2022). "However, the study on pancreatic cell lines and clinical samples using LCM and direct sequencing revealed that the EGFR gene is highly conserved in pancreatic cancer and contradicted its association with PC prognosis, leaving room for other explanations of the relevance of EGFR mutation in PDAC." (PMID 36498893, 2022). "We hypothesize that targeting SIRT7 might be beneficial for treating EGF signaling-dependent cancers, e.g., triple-negative breast cancers with increased EGFR expression and activity, colorectal and pancreatic cancers that harbor Ras mutations and NSCLCs with EGFR mutations." (PMID 34433808, 2021). "In addition, CDK1 and EGFR were significantly associated with the OS of pancreatic cancer." (PMID 34957301, 2021). "However, inhibitors of EGFR still show efficacy in some KRAS mutated pancreatic cancer cell lines." (PMID 22367239, 2013). "Moreover, the EGFR systems and associated signaling pathway could be promising targets for pancreatic cancer treatment." (PMID 22244109, 2012). "A recent study demonstrated complete regression of KRAS-driven pancreatic cancer upon systemic ablation up- and downstream signaling proteins EGFR and C-RAF." (PMID 42030284, 2026). "faecalis promotes pancreatic cancer cell proliferation through the activation of the Toll-like receptor-reactive oxygen species-epidermal growth factor receptor signaling pathway." (PMID 42274262, 2026). "In a different study, tetrahydroxycurcumin decreased cell survival and promoted apoptosis in lung and pancreatic cancer cell lines by downregulating EGFR and cyclooxygenase‐2 (COX‐2)." (PMID 41179371, 2025). "In colorectal and pancreatic cancers, additional co-mutations in KRAS (non-G12C alleles), EGFR, PIK3CA, BRAF, and MAP2K1 are frequently detected at baseline and are linked to primary resistance, underscoring the importance of comprehensive NGS at diagnosis." (PMID 40940900, 2025). "Studies have shown that there is high or abnormal expression of EGFR in many solid tumors, including pancreatic cancer." (PMID 40308779, 2025). "It has been demonstrated that rhein can restore chemosensitivity in the SMMC-7721 liver cancer cell line to doxorubicin and in pancreatic cancer cells to EGFR inhibitors by inhibiting mitochondrial energy metabolism and the STAT3 pathway, respectively." (PMID 40572668, 2025). "Hbegf-Egfr/Erbb2 is one of the main contributors to EGF signaling, and EGFR-activated myo-CAFs can promote pancreatic cancer metastasis." (PMID 40538442, 2025). "The overexpression of EGFR is a recurrent phenomenon in pancreatic cancer, correlating with the malignancy’s aggressive disposition and its resistance to treatment." (PMID 39916650, 2025).